Y_RNA (Y RNA )
Gene: Miscellaneous RNA gene on chromosome 10 (100,907,174 to 100,907,280, reverse strand). Ensembl gene ENSG00000222072.
Homologues: Orthologues: chimpanzee Y_RNA (94% identical). Paralogues in human: RNY3P1 (79% identical), Y_RNA (79% identical), Y_RNA (78% identical), RNY3 (77% identical), RNY3P4 (77% identical), Y_RNA (77% identical), Y_RNA (76% identical), RNY3P11 (75% identical), Y_RNA (75% identical), RNY3P5 (74% identical), Y_RNA (74% identical), Y_RNA (73% identical), and 89 more.